FABP4 (fatty acid binding protein 4)
Diseases named in the same sentence as FABP4 in open-access papers (continued):
Sharing a sentence is not in itself a finding about the gene and the disease.
Obesity (continued). "Experimental studies showed the elevation of circulating FABP4 level was associated with obesity, insulin resistance, diabetes mellitus, hypertension, cardiac dysfunction, atherosclerosis, and CAD events." (PMID 26517713, 2015). "Previous studies indicated that circulating FABP4 levels was increased in overweight and obese subjects compared with lean controls and was associated with markers of insulin resistance and obesity." (PMID 24593955, 2014). "Recent studies have shown secretion of FABP4 from adipocytes and association of elevated serum FABP4 level with obesity, insulin resistance, hypertension, and atherosclerosis." (PMID 25142635, 2014). "In the present study, we found that FABP4 level is associated with clinical parameters of obesity, insulin resistance, dyslipidemia, and high blood pressure even in asymptomatic apparently healthy subjects with no pharmacological treatments." (PMID 24278421, 2013). "Obesity is associated with increased secretion of metabolically adverse adipokines such as fatty acid binding protein-4 (FABP4) and reduced secretion of metabolically protective adipokines such as adiponectin." (PMID 24205333, 2013). "Recent clinical studies have shown that elevation of serum FABP4 is associated with obesity, insulin resistance, hypertension, and atherosclerosis." (PMID 24278421, 2013). "Epidemiological studies in different ethnic groups demonstrate a close association between serum levels of FABP4 and a cluster of obesity-related cardiometabolic risk factors." (PMID 23119072, 2012). "In cross-sectional studies including overweight or moderately obese patients, FABP4 was closely associated with obesity and MS." (PMID 23139800, 2012). "FABP4 is predominantly expressed in adipose tissue, and its circulating levels are linked with obesity and a poor atherogenic profile." (PMID 23139800, 2012). "In summary, we observed a decrease in FABP4 expression in adipose tissue inversely associated with obesity, with the insulin-resistance status being an important determinant involved in the tissue expression." (PMID 23139800, 2012). "FABP4 is a specific carrier protein for fatty acids in adipocytes; elevated FABP4 serum levels have been associated with obesity and the metabolic syndrome in human studies." (PMID 22588786, 2012). "It has recently been reported that FABP4 is detected in serum and cultured adipocyte supernatants and that the serum concentration of FABP4 is associated with obesity, type 2 diabetes, and cardiovascular diseases." (PMID 22121495, 2011). "Second, recent studies have shown that elevation of serum FABP4 is associated with obesity and insulin resistance, risk factors of atherosclerosis, and carotid atherosclerosis." (PMID 22102888, 2011). "Recent studies have shown that FABP4 is secreted from adipocytes and that FABP4 level is associated with obesity, insulin resistance, and atherosclerosis." (PMID 22102888, 2011). "Our current findings are in close agreement with the only 2 other published studies in children, in which obesity was a risk factor for elevated plasma FABP4 levels." (PMID 20156355, 2010). "Thus, our research question focused more on the mechanism underlying the association between pre‐diagnostic obesity and mortality, making the assessment of pre‐diagnostic FABP‐4 as an obesity biomarker particularly relevant." (PMID 40857027, 2026). "Increased circulating concentrations of FABP‐4 were observed in individuals with obesity as compared to those with normal‐weight, and a Mendelian Randomization (MR) study found a strong positive association between BMI and circulating FABP‐4 concentrations." (PMID 40857027, 2026). "FABP‐4 may also be involved in the progression of cancer indirectly by promoting insulin resistance and inflammation, two potential pathways in which obesity is implicated in CRC progression." (PMID 40857027, 2026). "FABP4 has a marked impact on the metabolic dysregulation associated with obesity and aging." (PMID 39843629, 2025).
Obesity (continued). "Furthermore, the expression of FABP4 regulates the development of obesity‐associated breast cancer and pancreatic cancer." (PMID 40107973, 2025). "The cross-sectional nature of our research restricts our ability to infer causative effects, suggesting that FABP4 may function as both a contributor to and a biomarker for diabetes and obesity." (PMID 38731797, 2024). "Circulating FABP4 bridges tumor-associated stromal cells to tumor stem cells and integrates adipokines to tumor-promoting signaling and lipid metabolism, thereby representing a new molecular link underlying obesity-associated breast cancer risk and mortality." (PMID 39054536, 2024). "Our study demonstrates a significant association between FABP4 levels and increased body weight, suggesting that it could be a potential target for obesity treatment." (PMID 38731797, 2024). "Moreover, fatty acid binding protein 4 (FABP4) secreted by adipose tissue enhances tumor stemness and aggressiveness by activating the IL-6/STAT3/ALDH1 axis in breast cancer, suggesting that plasma FABP4 is a new link between obesity and cancer risk." (PMID 39125923, 2024). "Therefore, the rationale for the current study is to investigate the association between FABP4, diabetes, and obesity and to explore the influence of age and ethnicity in a cohort from the Kuwait Diabetes Epidemiology Program (KDEP) study." (PMID 38731797, 2024). "In the current analyses, it was clear that the FABP4 levels demonstrated statistically significant positive associations with obesity markers including BMI (r = 0.496, p < 0.001), hip circumference (r = 0.463, p < 0.001), and waist circumference (WC) (r = 0.436, p < 0.001)." (PMID 38731797, 2024). "Moreover, given the pathogenic role of FABP4 in obesity-associated diseases, including diabetes, atherosclerosis and other cardiovascular diseases." (PMID 39054536, 2024). "There is a positive association of FABP4 with obesity and T2DM." (PMID 37920605, 2023). "However, a positive association of FABP-4 and CRC risk in women was observed in the biomarker analysis before adjustment for body size, suggesting that the positive association was largely explained by the upregulation of FABP-4 in obesity." (PMID 37833736, 2023). "Recent studies also demonstrated that FABP4 promotes obesity-associated breast cancer development." (PMID 37609286, 2023). "With regards to FABP4, evaluated levels of circulating FABP4 have been associated with arterial hypertension, type 2 diabetes mellitus, insulin resistance, obesity, atherosclerosis, cardiovascular disorders, abnormal QTc interval, kidney damage, cardiac dysfunction, and fatty liver disease." (PMID 37255976, 2023). "Based on observations in breast cancer FABP-4 has been suggested as a factor that may promote obesity-associated cancer initiation and progression." (PMID 37833736, 2023). "As noted for WD-fed MR-Intact mice, WD also downregulated genes associated with extracellular matrix in SMC-MR-KO mice (Online Resources 26 and 27) and top upregulated genes also included those implicated in diabetes and obesity, such as Cd36, Txnip, Angptl4, Cyp1a1, and Fabp4." (PMID 36988733, 2023). "Elevated FABP4 levels are associated with obesity and metabolic disease." (PMID 35223953, 2022). "Recent studies have demonstrated that adipocytes and macrophages can secrete FABP4 when induced by external factors, and circulating FABP4 could function as a novel adipokine linking obesity-associated diseases." (PMID 36060264, 2022). "Here, we comprehensively investigated obesity epidemiology and the biological mechanisms associated with the functions of FABP4 that may explain this effect." (PMID 36060264, 2022). "A deeper and more comprehensive understanding of how FABP4 signaling is involved in obesity-associated tumors could improve the potential of developing new therapeutic targets and strategies for tumor treatment." (PMID 36060264, 2022).
Obesity (continued). "Obesity may lead to an increased risk of cancer, and FABP4, as a member of the fatty acid-binding protein family, plays an important role in lipid regulation." (PMID 36532833, 2022). "Hence, we aimed to investigate the role of FABP4 in obesity-associated carcinogenesis in terms of its molecular mechanisms and therapeutic significance." (PMID 36060264, 2022). "This review leads us to understand how FABP4 signaling is involved in obesity-associated tumors, which could increase the potential for advancing novel therapeutic strategies and molecular targets for the systematic treatment of malignant tumors." (PMID 36060264, 2022). "In humans, serum FABP4 has been associated with obesity and insulin resistance." (PMID 34480568, 2022). "FABP4 is associated with obesity, insulin resistance, and T2D." (PMID 35647197, 2022). "Recent research demonstrated that FABP4 can promote obesity-associated BC development and may be a novel player linking obesity and BC risk." (PMID 35965527, 2022). "Likewise, FABP4, also upregulated in FF animals, is also expressed mainly by adipocytes but in contrast has increased levels associated with obesity and insulin resistance." (PMID 36118759, 2022). "Cross-sectional studies have shown that an elevated circulating FABP4 level is associated with obesity, insulin resistance, type 2 diabetes mellitus, hypertension, dyslipidemia, dysregulation of purine metabolism, atherosclerosis and disturbance of the heart, liver and kidney." (PMID 33597568, 2021). "Detection of serum FABP4 levels could be reflective of potential risk for metabolic diseases, such as obesity and T2D." (PMID 34174950, 2021). "Additionally, the adipocyte protein FABP4 has been previously associated to obesity and metabolic syndrome." (PMID 32214011, 2020). "Dysregulated FABP4 has been associated with obesity and NAFLD." (PMID 33603666, 2020). "The study showed that parental obesity was associated with significantly higher serum levels of FABP4 and leptin receptor in their offspring, whereas parental DM was linked to lower adiponectin but higher retinol binding protein 4 concentrations in the offspring." (PMID 30818771, 2019). "FABP4 is mainly expressed in differentiated adipocytes and macrophages, and previous studies have focused on its association with metabolic syndrome and its related components, especially obesity." (PMID 31651326, 2019). "Several studies have shown that FABP4 is closely associated with obesity and MS." (PMID 30575815, 2019). "In recent years, studies have found that FABP4 may play an important role in metabolic syndrome and the pathogenesis of liver cancer caused by obesity." (PMID 31651326, 2019). "For example, in diabetes and obesity, there is a significant association between parental history of obesity and diabetes and levels of serum fatty acid-binding protein 4, retinol-binding protein 4, and adiponectin, favouring obesity the risk developing of these disorders in offspring." (PMID 31582905, 2019). "Among adipokines, lipocalin-2 and fatty acid binding protein −4 (FABP-4), members of the superfamily of lipocalins, have been investigated as markers for adipose dysfunction associated with obesity and insulin resistance, and recently with coronary artery disease." (PMID 29304747, 2018). "Higher circulating FABP4 levels were associated with obesity and other metabolic syndromes." (PMID 29340091, 2017). "Thus, overexpression of FABP4 is involved in critical metabolic and pro-inflammatory aberrations associated with the complex pathogenesis of obesity and steatosis." (PMID 28933365, 2017). "However, recent studies have shown that FABP4 is released from adipocytes and that serum concentration of FABP4 is associated with obesity, insulin resistance, diabetes, hypertension, cardiac dysfunction, atherosclerosis and inflammatory markers." (PMID 25506691, 2014).
Obesity (continued). "Moreover, some of studies shown that circulating FABP4 levels were increased in overweight and obese subjects compared with lean controls, and was associated with markers of insulin resistance and obesity." (PMID 24593955, 2014). "Furthermore, elevated serum concentration of FABP4 has been shown to be associated with obesity, insulin resistance, hypertension and atherosclerosis." (PMID 25142635, 2014). "Furthermore, increased serum concentration of FABP4 has been shown to be associated with obesity, type 2 diabetes, hypertension, and cardiovascular diseases." (PMID 24278421, 2013). "Several studies have linked FABP4 levels to obesity, T2D and MS." (PMID 22709426, 2012). "Several studies have linked FABP4 circulating levels with obesity and other diseases." (PMID 23139800, 2012). "Correlation analysis of the three measured adipokines revealed that serum FABP4 level correlated significantly with parameters associated with obesity, including BMI (R = 0.25, P = 0.002) and systolic (R = 0.15, P = 0.01) and diastolic (R = 0.18, P = 0.004) blood pressure." (PMID 23119072, 2012). "However, our study demonstrates an inverse association between obesity and FABP4 adipose tissue expression." (PMID 23139800, 2012). "The decrease in the phosphorylation of AMPK's substrates and increase of FABP4 expression in DDT knockdown adipocytes led us to speculate that the down-regulation of DDT expression is involved in glucose intolerance caused by obesity." (PMID 22428043, 2012). "However, a few studies showing maintained insulin sensitivity despite diet-induced obesity and hepatosteatosis exist, e.g. FABP4 and 5 as well as Elovl6 deficient mice." (PMID 21738729, 2011). "Mice with combined deficiency of FABP4 and FABP5 (Fabp4−/−Fabp5−/−) on a high-fat diet or in a genetic obesity model exhibit remarkably improved insulin resistance and protection against type 2 diabetes and fatty liver disease more than did FABP4- or FABP5-deficient mice." (PMID 22121495, 2011). "Such methodological approach may have artificially reduced the impact of obesity on FABP4 levels as well as the magnitude of the association of any given FABP4 allelic variant with the degree of metabolic dysfunction or FABP4 plasma levels." (PMID 20156355, 2010). "The presence of selective SNPs in the FABP4 gene may account for increased risk for insulin resistance or systemic inflammation in the context of obesity." (PMID 20156355, 2010). "Furthermore, gene variants in FABP4 appear to differentially contribute to the pro-inflammatory or diabetogenic potential of obesity during childhood." (PMID 20156355, 2010). "Although a high-fat diet (HF) and/or HF-mediated obesity have been clearly linked to the progression of prostate cancer, with FABP4 potentially playing a critical role in this relationship, the mechanisms by which FABP4 facilitates this interaction remain unclear." (PMID 41226657, 2025). "In this context, the role of FABP4 becomes crucial; FABP4 plays a pivotal role in the transportation and intracellular storage of FAs and is implicated in numerous metabolic and inflammatory pathways associated with obesity and cancer, as evident in our in vitro study." (PMID 39823981, 2025). "Researchers also found significant increases in norepinephrine, glucagon, and fatty acid binding protein 4 (FABP4) after consuming diets containing propionate, suggesting that propionate may be a “metabolic disruptor” that increases the risk of diabetes and obesity." (PMID 39606109, 2024). "Therefore, it is possible that FABP4 may be associated with obesity, chronic kidney disease, diabetes mellitus and metabolic syndrome, thereby contributing to lower HRV in patients with chronic schizophrenia." (PMID 37255976, 2023).
Obesity (continued). "Clarifying the role of FABP-4 in CRC development is important because it may potentially serve as an obesity-associated biomarker that may help identify individuals at high risk of disease who might specifically benefit from primary or secondary prevention strategies." (PMID 37833736, 2023). "Deletion of FABP4 increases PPARγ expression, and lipogenesis and insulin sensitivity in adipocytes, suggesting that FABP4-dependent inhibition of PPARγ might favor insulin resistance and induction of inflammatory pathways associated with obesity." (PMID 32856199, 2020). "Additionally, animal models deficient in FABP4 present reduced hyperinsulinemia and insulin resistance in obesity, which is suggestive of this adipocytokine’s effect on the interdependence between obesity and insulin resistance." (PMID 30818771, 2019). "Recent studies also showed that FABP4 is one of the novel adipocyte-derived bioactive molecules referred to as adipokines and that elevated circulating FABP4 level is associated with obesity, insulin resistance, hypertension, cardiac dysfunction and atherosclerosis." (PMID 25506691, 2014). "Therefore, we hypothesized that decreased FABP4 expression in adipose tissue linked to obesity could be compensated by an increased expression of FABP4 in peripheral tissues with the onset of IR." (PMID 23139800, 2012). "Furthermore, the frequency of the rs1054135 single nucleotide polymorphism in the FABP4 gene was higher in OB compared to NOB, and seemingly contributes to higher FABP4 levels, while the presence of rs16909233 is associated with insulin resistance in the context of obesity." (PMID 20156355, 2010). "In this regard, genetic variability at the FABP4 as evidenced by rs1054135, increased FABP4 plasma levels in both obese and non-obese children, and its relative preponderance in obese children suggests an interaction between obesity and FABP4 alleles to increase FABP4 circulating levels." (PMID 20156355, 2010). "When we dichotomized BMI into obesity (BMI ≥30 kg/m2) versus non‐obesity (BMI <30 kg/m2), the MP by FABP‐4 was higher for CRC‐specific mortality (38.5%, p = .005) than for non‐CRC‐specific mortality (21.9%, p = .03)." (PMID 40857027, 2026). "Studies in HFD mouse models have demonstrated that deleting FABP4 in macrophages reduces inflammation and provides protection against obesity‐related metabolic dysfunction." (PMID 40692664, 2025). "Overall, these findings showed that the activation of the mTORC1 pathway stimulated FABP4, leading to obesity‐related IVDD." (PMID 40090836, 2025). "In obesity, FABP4 is upregulated in adipocytes and macrophages, where it plays a critical role in lipid metabolism and insulin resistance." (PMID 40090836, 2025). "Here, we firstly revealed a causal correlation between obesity and IVDD via a two‐sample mendelian randomization analysis and identified fatty acid‐binding protein 4 (FABP4) as the potential regulator to associate IVDD and obesity." (PMID 40090836, 2025). "The inflammatory activities of FABP4 in different immune cells has been reported previously in the context of obesity, atherosclerosis, nonalcoholic fatty liver disease and rheumatoid arthritis (RA)." (PMID 40716098, 2025). "Increased concentrations of FABP4 have been detected in diabetic patients, leading to obesity and atherosclerotic lesions (reviewed in Furuhashi & Hotamisligil, 2008 ▸)." (PMID 40748030, 2025). "Our primary objectives are to investigate the causal relationship between obesity and IVDD and to identify the role of FABP4 in obesity‐induced IVDD and the molecular mechanisms by which FABP4 mediates ECM imbalance and angiogenesis." (PMID 40090836, 2025). "Targeting FABP4 effectively ameliorates nucleus pulposus dysfunction and angiogenesis in obesity‐related IVDD." (PMID 40090836, 2025). "Obesity promotes the progression of intervertebral disc degeneration (IVDD) through the mTORC1/FABP4 axis." (PMID 40090836, 2025).